E2F1 (E2F transcription factor 1)
Diseases named in the same sentence as E2F1 in open-access papers (continued):
Sharing a sentence is not in itself a finding about the gene and the disease.
breast carcinoma (continued). "In the TCGA, inferred E2F1 activity was significantly (FDR < 0.1) and positively correlated with sample HMT expression in 30/33 cancer types, for example breast cancer." (PMID 37883365, 2023). "Taken together, RPL5 inhibited the growth of breast cancer cells by modulating ERS and autophagy via the regulation of E2F1." (PMID 35293275, 2022). "The expression of MALAT1 was shown to be enhanced by METTL3 through recruitment of E2F transcription factor 1 (E2F1), resulting in transcription of anterior gradient 2 (AGR2), and subsequent adriamycin resistance in breast cancer." (PMID 35721510, 2022). "E2F1, as the transcription factor directly bound to the promoter and regulate the expression of SEC61G, has been validated in breast cancer." (PMID 36712687, 2022). "E2F1 and c-Myc are overexpressed in basal breast cancers from NHB women, FoxM1 in Her2 + breast cancers from NHW women, FoxM1, E2F1 and E2F2 in Luminal A breast cancers from NHB women." (PMID 36494865, 2022). "The researchers discovered that E2F1 increased Nanog expression at the transcriptional level, suggesting that the LINC00511/E2F1 axis boosted breast cancer stemness and carcinogenesis." (PMID 35790898, 2022). "METTL3 regulated MALAT1/E2F1/AGR2 pathway and subsequently controlled Adriamycin resistance in breast cancer." (PMID 36212476, 2022). "Overexpression of E2F1 and E2F3 has been reported to be overexpressed and have a tumor-promoting effect in many cancers including lung cancer, breast cancer, and ovarian cancer." (PMID 34316028, 2021). "We initially focused on transcription factors with reported links to breast cancer, and found that 16 transcription factors including HIF-1α, MYC, FOXP3, and E2F1 were predicted to target the JFK locus." (PMID 34336836, 2021). "E2F1 ablation has been shown to decrease metastasis in MMTV-Neu and MMTV-PyMT transgenic mouse models of breast cancer." (PMID 33947907, 2021). "Mechanistically, we showed that transcription factor E2F1 directly bound to the promoter of SEC61G and regulated its expression in breast cancer cells." (PMID 34039955, 2021). "Concomitantly, E2F1 was found to act as a downstream target of miR-185-3p and promote CSC stemness properties through the LINC00511/miR-185-3p/E2F1/Nanog axis in breast cancer." (PMID 34476219, 2021). "Our results reveal that an elevated expression of transcription factor E2F1 and increased CpG hydroxymethylation of the E2F1 binding motif conjointly induce ESRP1 expression in breast carcinoma." (PMID 34362878, 2021). "The data presented here, combined with the previously established literature, show key roles of E2F1 and E2F2 as contributing factors in the genomic instability seen in breast cancer." (PMID 33087787, 2020). "We demonstrated that E2F1 induces KIF26A transcription and promotes cell cycle progression via the CDK–RB–E2Fs feedback loop in breast cancer." (PMID 33505901, 2020). "The present study demonstrated that KIF26A, directly upregulated by E2F1, promoted cell proliferation and cell cycle progression via CDK–RB–E2Fs feedback loop in breast cancer." (PMID 33505901, 2020). "Our findings uncovered for the first time that E2F1 and CCND1 positively modulated PTX-resistance in breast cancer cells." (PMID 32796817, 2020). "HBXIP can act as a transactivator by activating certain genes including c-Myc, E2F1, STAT4, and Sp1 to play a crucial role in the progression of breast cancer." (PMID 32850453, 2020). "More intriguingly, we found the expression levels of E2F1 and CCND1 were positively correlated with the methylation of miR-93 promoter locus, using breast cancer samples (n = 614) in TCGA database." (PMID 32796817, 2020).
breast carcinoma (continued). "Present study revealed significant down-regulation of cell cycle and DNA damage response genes, including E2F1, E2F2, RAD51, and CCNB1 in breast cancer cells treated with palbociclib." (PMID 31548560, 2019). "Doxorubicin treatment upregulated miRNAs-449 and DNA-damage responder factors E2F1 and E2F3 in triple negative breast cancer sensitive breast cancer cells, while expression remained unaltered in resistant ones." (PMID 30926829, 2019). "Results found that LINC00511 functions as a miR-185-3p ‘sponge’ to harbor its expression, and then target E2F1 protein, confirming the role of LINC00511/miR-185-3p/E2F1 axis in breast cancer." (PMID 30482236, 2018). "As regarding to the role of lncRNAs on the breast cancer CSCs properties, we discover the vital pathway of LINC00511/miR-185-3p/E2F1/Nanog." (PMID 30482236, 2018). "In a previous study, we demonstrated that E2F1, E2F2, and E2F3a are highly deregulated in breast cancer and their individual overexpression induced CA and CIN in MCF10A mammary epithelial cells." (PMID 29100415, 2017). "More specifically, TGFBR1 and FGFR1 in combination with highly expressed E2F1 induce the most invasive phenotype in bladder cancer, whereas in breast cancer, it is the combined action of TGFBR2, EGFR, and E2F1 that triggers high levels of invasiveness." (PMID 28775339, 2017). "Kaplan-Meier plots identified correlations between individual or combined overexpression of E2F1, E2F3a, Mps1/TTK, Nek2, BubR1, or Hec1 and poor overall and relapse-free survival of breast cancer patients." (PMID 29100415, 2017). "The in silico simulation results indicated that high levels of E2F1–TGFBR1–FGFR1 in bladder cancer and E2F1–TGFBR2–EGFR in breast cancer constitute a molecular signature that represent the most aggressive phenotype." (PMID 28775339, 2017). "MALAT1 was reported to be an endogenous regulator of breast cancer progression by down-regulating miR-124 and activating the CDK4/E2F1 signaling pathway." (PMID 28439401, 2017). "Our laboratory has demonstrated that deregulation of regulators of the centrosome cycle, mitosis, and G1/S phase including Cdk4, the E2F activators (E2F1, E2F3a), Nek2, Sgo1, and Mps1/TTK are required to maintain high CA and CIN in Her2+ breast cancer cells." (PMID 29100415, 2017). "Taken together, these findings clearly demonstrate that autophagy targets and degrades E2F1, thereby leading to cyclin D1 induction in leptin-treated MCF-7 breast cancer cells." (PMID 29312618, 2017). "Taken together, these data indicate that miR-302b, by targeting E2F1, negatively affects ATM expression levels in breast cancer cells of different origin." (PMID 26623722, 2016). "Approximately 56% of these genes have been previously identified as up-regulated at 24 h post-estrogen stimulation, including known breast cancer genes BRCA1, BRCA2, and E2F1." (PMID 27539783, 2016). "For instance, the most studied member E2F1 maintained centrosome amplification and inhibited the promoter activity of the tumor suppressor gene ARHI, contributing to the tumorigenesis of breast cancer." (PMID 26992224, 2016). "We established a gene expression signature of Rb loss-of-function (RBsig) by identifying genes correlated with E2F1 and E2F2 expression in breast cancers within The Cancer Genome Atlas." (PMID 27634906, 2016). "For example, an L-FFL motif consisting of the TF E2F1, the miRNA miR-15b and the lncRNA IQCH-AS1 was dysregulated in breast cancer, lung squamous cell carcinomas, and lung adenocarcinoma." (PMID 27322142, 2016).
breast carcinoma (continued). "Previous research appeared to support the argument that CARM1 is oncogenic in that the reduction of CARM1 expression decreased E2F1 levels and cell cycle progression in MCF7 breast cancer cells." (PMID 26030442, 2015). "In breast cancer cells, a positive feedback loop between CIP2A and E2F1 had been shown to define the cell-intrinsic senescence sensitivity." (PMID 25015035, 2014). "Current data suggests that KDM2A works in conjunction with E2F1 to affect FLT-1 and KDR expression in endothelial cells and MMP expression in breast cancer cells." (PMID 25029110, 2014). "In this study, PD-0332991 treatment decreased expression of E2F1 and reduced HOXB9 and its target genes in MCF7 breast carcinoma cells." (PMID 25136922, 2014). "Our in vitro analysis identified the TFBS of the HOXB9 promoter region and suggested that E2F1 is a direct regulator of HOXB9 expression; these data support the strong correlation we found between E2F1 and HOXB9 in clinical breast cancer samples." (PMID 25136922, 2014). "We also report that a highly specific AHR agonist significantly (P < 0.05) inhibits the expression of E2F1, CCND1 (known as Cyclin D1), MYB, SRC, JAK2, and JUND in breast cancer cells." (PMID 24171117, 2013). "As expected, concordance analysis between ER+ and ER− breast cancer DRGEPs and TREG signatures of ERα and E2F1 activity demonstrated involvement of E2F1 regulation in both DRGEPs (p-value = 7.0×10−14 for ER+ and p-value = 1.3×10−72 for ER−)." (PMID 24039560, 2013). "This study demonstrates that simultaneous targeting of DNA and E2F1 methylation is an effective epigenetic treatment that reactivates RASSF1A expression and induces apoptosis in breast cancer cells." (PMID 23251702, 2012). "In transiently transfected MCF-7 breast cancer cells, the RIP140 promoter is transactivated by overexpression of E2F1/DP1." (PMID 22629304, 2012). "Our observations suggest a possible relationship between E2F1 and KIAA0191 expression that is relevant to the pathogenesis of breast cancer." (PMID 21453498, 2011). "In particular, in comparison with HMEC, several breast cancer cell lines (including 4T1 mouse mammary tumor cell line, and human breast cancer cell lines BT-20, MCF-7 and SkBr-3) express high levels of E2F1 and h-eag1 proteins." (PMID 21655246, 2011). "E2F1, 4 and their complexes with HDAC play an important role in downregulating the expression of the maternally imprinted tumor suppressor gene ARHI in breast cancer cells." (PMID 21962223, 2011). "In a set of 317 primary breast cancers patients with known clinical outcome (STB data set), we evaluated E2F1 mRNA expression levels with respect to other proliferation markers, ER and ERBB2 status and clinical outcome." (PMID 17535433, 2007). "Another example relevant for breast cancer is the hsa-miR-17-5p/EREG pair of miRNA and predicted target gene that putatively form FFLs with E2F1, EGR2, FOXJ2 and RUNX1." (PMID 17971223, 2007). "It has been demonstrated that the level of E2F1 and E2F3 expression were related to the clinical outcomes of multiple tumors, such as lung cancer, pediatric retinoblastoma, breast cancer, hepatocellular carcinoma." (PMID 40070576, 2025). "In addition, XBP1s overexpression reversed the palbociclib‐induced downregulation of E2F1 target genes and impaired the therapeutic efficiency of palbociclib in HR+/HER2− breast cancer." (PMID 40940685, 2025). "Comparing to Srsf3 WT liver cancer, Srsf3 KO significantly increases Sox4, E2f1, Trpv4, Trim6, and Myc expression, but does not so in Erbb2 breast cancer." (PMID 40568073, 2025). "HBV infection may lead to increased expression levels of several key genes in breast cancer cell lines, including CDK2, PCNA, CCNE2, CXCL8, E2F1, and CASP3." (PMID 40697521, 2025). "In vivo cell experiment, we confirmed that HBV infection may lead to increased expression levels of several key genes in breast cancer cell lines, including CDK2, PCNA, CCNE2, CXCL8, E2F1, and CASP3." (PMID 40697521, 2025).
breast carcinoma (continued). "The same as in this report, PURα and E2F1 were co-localized in the nuclear fraction of breast cancer cells, and AGPG disrupted the formation of the PURα/E2F1 complex to activate E2F signaling, facilitating ER-positive breast cancer cell proliferation and endocrine resistance." (PMID 39000020, 2024). "In breast cancer datasets, we found significant upregulation of both centrosome clustering proteins KIFC1, AURKB, BIRC5, and CDCA8 and the oncogenes FOXM1, ATAD2, and E2F1 in tumor samples compared to normal samples." (PMID 39335162, 2024). "E2F1 and E2F4 induce whereas pRb/RBL2 reduce WNT ligand expression (e.g. WNT7A, WNT7B, WNT10A, WNT4) thereby regulating self-renewal, chemoresistance and invasiveness of CSCs in both PDAC and breast cancer, and fibroblast proliferation." (PMID 38678032, 2024). "In addition to E2F1 and SMAD3, several other transcription factors have been identified to down-regulate hTERT transcription in breast cancer." (PMID 37612721, 2023). "Our group pioneered the study of SGO1 in breast cancer in general by demonstrating, using cBIOPORTAL, that the overexpression of SGO1 in breast tumors correlates with the overexpression of the E2F transcriptional activators E2F1, E2F2, and E2F3." (PMID 37122033, 2023). "This microRNA plays a pivotal role in the initiation of breast cancer and may activate the WNT and E2F1 pathways during the epithelial–mesenchymal transition process." (PMID 35741808, 2022). "Furthermore, E2F1 reversed the effects of RPL5 on ERS and autophagy, suggesting that RPL5/E2F1 modulates ERS and autophagy in breast cancer." (PMID 35293275, 2022). "Given its oncogenic roles in tumor progression, it is not surprising that E2F1 activity is higher in breast cancer tissue as compared to normal tissue with the highest activity in aggressive TNBC tumors." (PMID 35655310, 2022). "Briefly, HIF-1α overexpression, but not FOXP3 nor E2F1, has been reported to be closely related to high histological grade, lymph node metastasis, large tumor size, and increased angiogenesis in breast cancer, which is consistent with the function of JFK." (PMID 34336836, 2021). "Whether E2F1/SEC61G contributes to the metastasis of advanced breast cancer and targeting E2F1/SEC61G to improve drug-resistance in breast cancer treatment will be further studied." (PMID 34039955, 2021). "Moreover, there have been reported direct interactions of E2F1 and retinoblastoma protein (RB) with the promoter of RECQL4 in prostate cancer cells and RECQL4 with BIRC5 in breast cancer cells." (PMID 33541355, 2021). "Further analysis demonstrated that the expression of cell cycle-related genes (CDC6, CDC25A, CDK1, ATM, E2F1, and MKI67) were much higher in breast cancer patients of 3 target genes high expression group or MIR3613 deletion group compared with their counterpart, respectively." (PMID 33494814, 2021). "Finally, we demonstrated that the E2F1/SEC61G axis regulated glycolysis and chemo-sensitivity of Herceptin in breast cancer cells." (PMID 34039955, 2021). "Moreover, we revealed that the E2F1/SEC61G axis modulated glycolysis and Herceptin chemo-sensitivity in breast cancer cells." (PMID 34039955, 2021). "In addition, the data from an online database indicated that miR-320a could bind to the 3′-UTR of E2F1, which is a well-known transcriptional activator that has been determined to be extensive involved in tumour progression in such cancers as bladder cancer 42 breast cancer 43, and lung cancer." (PMID 34659533, 2021). "Gene expression analysis on breast cancer tissue of 35 out 222 patients (N = 4 with CNV > 2 and N = 31 with CNV = 2 in blood) has revealed a positive and statistically significant correlation between E2F1 expression and number of copies (p = 0.004)." (PMID 33691613, 2021). "Human breast tumors resemble mouse mammary tumors in that low E2F1 activity does not lead to vast gene expression changes." (PMID 33947907, 2021).
breast carcinoma (continued). "We speculate that the underlying mechanism of miR-20b-5p contributing to the malignant progression of breast cancer is that miR-20b-5p overall upregulates both CCND1 and E2F1 via bidirectional regulation." (PMID 33008330, 2020). "The induction of HOXB9 expression by E2F1 was observed in several breast cancer cell lines and a significant correlation between E2F1 and HOXB9 was revealed in clinical breast cancer samples indicating their potential role in breast cancer progression." (PMID 33171691, 2020). "Some studies demonstrated a repressive effect between ER stimulation, especially ERα, and E2F1 gene expression, in contrast, stimulation of E2f1expression was observed by ERα in normal MCF-7 breast cancer cell lines and cell lines that were tolerated to Tamoxifen." (PMID 32742594, 2020). "However, the explicit effects of E2F1 and CCND1 on chemoresistance of breast cancer remains poorly understood." (PMID 32796817, 2020). "Furthermore, E2F transcription factors, from E2F1 to E2F8, have been reported as possible biomarkers for breast cancer, although their expression patterns and prognostic significance have been inconsistent in previous studies." (PMID 32650578, 2020). "Increased E2F1 upregulates NANOG, contributing to stemness in breast cancer." (PMID 32244924, 2020). "We next assessed the possibility that ZC3H18 might affect E2F1 and DNMT1 differently in ovarian and breast cancer cells." (PMID 31604914, 2019). "To investigate the prevalence of TEs in breast cancer-associated TFBSs, we mapped the genome-wide binding sites for C/EBPβ, E2F1 and MYC in MCF7 breast cancer cells by re-analysing publicly available chromatin immunoprecipitation sequencing (ChIP-seq) datasets." (PMID 31061680, 2019). "Numerous studies have reported that E2F1 expression was significant for poor prognosis in malignancies such as oesophageal carcinoma, hepatic cellular carcinoma (HCC), pancreatic cancer, non-small cell lung cancer and breast cancer." (PMID 30487158, 2018). "Using cBioPortal analysis of the TCGA database, we next addressed whether individual genes co-occurred in breast cancers and found significant correlations between E2F1 overexpression and E2F2, E2F1 overexpression and E2F3, and E2F2 overexpression and E2F3." (PMID 29100415, 2017). "Finally, we demonstrated that miR-302b negatively regulates E2F1 and, indirectly, ATM, using two different cellular models of breast cancer, BT-549 (TNBC) and T47D (luminal breast cancer)." (PMID 26623722, 2016). "Therefore, the downregulation of E2F1, CDK4, cyclin D1 and cyclin D3 and upregulation of p27 and p21 in breast cancer cells likely contributed to the G1 cell cycle arrest induced by 5a." (PMID 25766325, 2015). "Taken together, these results indicate that the E2F1-mediated expression of MMP2, MMP9, MMP14, and MMP15 might be repressed by KDM2A, eventually hindering the migration and invasion of breast cancer cells." (PMID 25029110, 2014). "Upregulation of the activating E2F genes was also found in basal versus not-basal breast cancer: E2F1 (FC = 2.01, P = 8.72E-06), E2F2 (FC = 1.98, P = 2.97E-07), and E2F3 (FC = 1.95, P = 8.13E-17)." (PMID 25161863, 2014). "Then, the consensus E2F1 (con.E2F1) and mutated E2F1 (mut.E2F1) were transiently transfected into 293 T cells, and primary non-mutated and BRCA1-mutated breast cancer and their corresponding normal breast cells." (PMID 24502362, 2014). "We thus investigated whether PD-0332991 also inhibits E2F1 expression in BT-549 breast cancer cells, which has high expression of endogenous HOXB9 and E2F1, compare to the control (MCF7 cells), and whether this treatment would affect HOXB9 expression." (PMID 25136922, 2014).